CD22 (CD22 molecule)
Diseases named in the same sentence as CD22 in open-access papers (continued):
Sharing a sentence is not in itself a finding about the gene and the disease.
Arthritis (5 papers, 2011 to 2021). Inflammation of a joint. "Potential biomarkers in early arthritis include differential infiltration by CD22+ve B cells and CD38+ plasma cells in patients with early arthritis differentiating RA vs. non RA inflammatory arthritis." (PMID 30761301, 2019). "Arguing against a role for B cells and CD22 is the observation that mice deficient in B cells or CD22 were still protected by IVIg from ITP and serum-induced arthritis." (PMID 27105835, 2016). "CD22-cal has been extensively characterized and used in animal models of arthritis, infection and type 1 diabetes." (PMID 21931827, 2011). "Approximately 50% of the animals treated with CD22-cal at days -6 and -1 before immunization still developed arthritis, albeit with a delayed onset and reduced severity." (PMID 21931827, 2011). "Clinical arthritis scores of those mice that did develop disease after late CD22-cal treatment were lower than those of the control mice but higher than those of the mice, which had received prophylactic treatment (right)." (PMID 21931827, 2011). "When CD22-cal was injected at days 3 and 8 after immunization, arthritis incidence was still reduced to approximately 50% of controls (left)." (PMID 21931827, 2011). "To investigate the role of B cells in G6PI-induced arthritis at different disease stages, we wished to use a B cell depleting immunoconjugate (anti-CD22 mAb conjugated to chalicheamicin, referred hereafter to as CD22-cal)." (PMID 21931827, 2011). "Here report that in vivo depletion of B cells with CD22-cal prevents but does not cure G6PI-induced arthritis." (PMID 21931827, 2011). "Nevertheless, other authors, using CD22-deficient mice in models of ITP and K/BxN arthritis, could not demonstrate a role for CD22 in the immediate anti-inflammatory activity of IVIG." (PMID 25657650, 2015). "Synovial membrane activation of JUN N-terminal kinase is increased in early RA, but not in undifferentiated forms of arthritis, and CD22+ and CD38+ cells distinguish RA from other forms of arthritis." (PMID 33968950, 2021).
CNS lymphoma (5 papers, 2021 to 2025). "Nonetheless, limited data compared the impact of ASCT plus CART versus sequential CD19/CD20/CD22 or targeting other tumor antigen CAR T-cell therapy on advanced r/r CNS lymphoma." (PMID 36483984, 2022). "One patient with primary and four patients with secondary CNS lymphoma each received one intravenous infusion of CD19-directed (2.2 × 106 to 7.1 × 106/kg body weight) and one infusion of CD22-directed CAR T-cells (3.1 × 106 to 7.0 × 106/kg)." (PMID 34065471, 2021). "Although there has been major concern that treatment of CNS disease may be paralleled by strong neurotoxic symptoms, only one case of severe ICANS in a CNS lymphoma patient receiving CD19 and CD22 directed CAR T-cells has so far been described." (PMID 34065471, 2021).
colon cancer (5 papers, 2019 to 2024). "It has been reported that CD22 functions as a regulator of B-cell response and is associated with oxaliplatin resistance in colon cancer, while ZNF114 potentially promotes non-small cell lung cancer (NSCLC) metastasis." (PMID 37934338, 2024). "Recently, a study using an oxaliplatin resistance-related gene signature (consisting of CD22, CASP1, CISH, and ALCAM) to predict the survival of patients with colon cancer found that this gene signature has a better predictive value." (PMID 36145360, 2022). "Thirdly, there is little research on the role of CD22, CASP1, and CISH in colon cancer, even though it plays an important role." (PMID 34026619, 2021). "Thereafter, we established a prognosis signature based on four genes [CD22, CASP1, CISH, and activated leukocyte cell adhesion molecule (ALCAM)] to evaluate the prognosis for colon cancer patients." (PMID 34026619, 2021). "Afterward, we established a model to predict the prognosis of colon cancer using four oxaliplatin resistance-related genes (ALCAM, CD22, CASP1, and CISH) on the basis of stepwise regression and LASSO Cox regression." (PMID 34026619, 2021). "The risk scores calculated based on the expression levels and coefficients of four mRNAs (ALCAM, CD22, CASP1, and CISH) might be used to precisely and independently predict the prognosis of colon cancer." (PMID 34026619, 2021).
viral infection (5 papers, 2020 to 2023). "CD22 blockade was sufficient to inhibit the immune dysregulation triggered by Notch1 signaling in Tregs in the poly I:C proxy viral infection model, highlighting the critical role of this molecule in MIS-C disease pathogenesis." (PMID 36282598, 2023). "Conversely, CD22 has been shown to play a role in controlling a viral infection." (PMID 32324805, 2020). "Overall, it is clear that viral infection modulates the phenotype of the novel DN3 subset such that these cells have reduced BAFFR and CD86 but elevated levels of FcRL5, CD22, and CD69 during severe disease." (PMID 36131937, 2022). "We next again assessed if immunization or viral infection influenced inhibitory receptor expression on DN2 B cells by measuring CD72 and CD22 surface expression." (PMID 36131937, 2022). "Because severe viral infection results in phenotypically activated unswitched and switched memory B cells, we sought to determine if activation of the memory B cell populations also coincides with a reduction in inhibitory receptors by memory B cells through evaluation of CD72 and CD22." (PMID 37638016, 2023). "This suggests that DN2 cells naturally have the largest capacity to signal through the BCR compared to other DN subsets, a process which may be independent of traditional inhibitory receptors (CD22, CD72, FcRL5) and/or that the function of inhibitory receptors is impaired during viral infection." (PMID 36131937, 2022).
B-cell neoplasm (4 papers, 2021 to 2024). A group of heterogeneous lymphoid tumors generally expressing one or more B-cell antigens or representing malignant transformations of B-lymphocytes. "A few dogs had aberrant CD3+ (7/37, 19%) or CD5+ (2/37, 5%) tumor cells; however, in all of these cases, tumor cells were CD21+ and CD22+, supporting a B cell neoplasm." (PMID 39224452, 2024). "Loss of antigen expression has been described as resistance mechanism to various immunotherapies, e.g. Blinatumomab and Rituximab, for several B-cell neoplasms, but comprehensive studies on the frequency of CD22 loss after InO treatment in B-ALL are lacking." (PMID 34331563, 2021). "Like other mature B cell neoplasms, FL expresses pan-B cell antigens (CD19, CD22, CD79a and PAX5), and is also by definition positive for germinal center markers, such as BCL6, HGAL and LMO2." (PMID 34898578, 2021).
colitis (4 papers, 2008 to 2026). Inflammation of the colon. "Thus, TNBS colitis was characterized by an absence of significant changes in markers of T cells (Thy1, Tcrb, Tcrg, Zap70, Lck), B cells (Ptprc -B220-, Ms4a1 -Cd20-, Cd22, Cd79b) and NK cells (Baat, Ncam1 -Cd56-, B3gat1 -Cd57-)." (PMID 18928539, 2008).
colorectal cancer (4 papers, 2021 to 2025). A primary or metastatic malignant neoplasm that affects the colon or rectum. "Transcriptomic profiling of oxaliplatin-resistant colorectal cancer (CRC) cells derived from DLD1 and HCT116 identified ALCAM activation with concurrent CD22, CASP1, and CISH suppression as key molecular features of oxaliplatin non-response." (PMID 41009436, 2025).
COVID-19 (4 papers, 2021 to 2023). A disease caused by infection with severe acute respiratory syndrome coronavirus 2. "BCR inhibitory gene expression was limited, but CD22 was detectable across B cell subsets in asymptomatic COVID-19, while FCGR2B, CD72 and PTPN6 expression was evident in B cells in severe COVID-19." (PMID 33879890, 2021). "Specifically, in the COVID-19 patient’s B cells, we detected a substantial increase in the expression of CD52, CD74, CD22 and CD79B and a decrease in CXCR4, CD69, INFGR1, PTPRC and LAMP1 transcripts with respect to control-derived B cells." (PMID 34944610, 2021). "In comparison to the COVID-19(-) PU controls, genes highly expressed in the TV group fell into categories that included neutrophil dysfunction (CD274, PADI2), inhibition of B and T cell responses (CD22, IRF4, ORAI1), and upregulation of pro-inflammatory response pathways (CARD8, MAPK7, IRF7, IFIH1)." (PMID 37026002, 2023). "In contrast, CD22 was minimally expressed on CD4+ Tconv cells of control individuals, patients with acute COVID-19, and patients with MIS-C, and it did not correlate with Notch1 expression in these cells." (PMID 36282598, 2023).
glioblastoma (4 papers, 2020 to 2023). The most malignant astrocytic tumor (WHO grade IV). "Genetic deletion or antibody blockade of SIRPα, CD22, CD33 and PD1 enhance the microglial phagocytic activities against Aβ and glioblastoma, making the receptors attractive therapeutic targets for treating AD and brain tumor." (PMID 37483607, 2023).
hemophagocytic lymphohistiocytosis (4 papers, 2021 to 2025). "A total of 32.8% of ALL patients who received CD22-targeted CAR T-cell therapy experienced hemophagocytic lymphohistiocytosis (HLH)/MAS." (PMID 36313658, 2022). "A clinical trial confirmed that anakinra is effective in the treatment of hemophagocytic lymphohistiocytosis (HLH) after CD22 CAR T-cell therapy in ALL patients." (PMID 34794490, 2021). "She achieved complete remission (CR) but experienced grade III CRS and hemophagocytic lymphohistiocytosis (HLH) 41 days after CD19-targeted CART (CART19) cells and CD22-targeted CART (CART22) cells infusion." (PMID 35719984, 2022).
lymph node metastases (4 papers, 2016 to 2025). "We analyzed the association between the expression of CD22 and clinicopathological features (age, depth of tumor invasion, lymph node metastasis, histologic grade, clinical stage, and Ki67 expression) of 97 TNBC patients (p < 0.05)." (PMID 36768478, 2023). "CD22 was one of the most differentially expressed genes in lymph node metastases of patients with metastatic breast cancer compared to primary breast tumors." (PMID 40362379, 2025). "The relationship between expression and clinical parameters reveals that CD22 may contribute to lymph node metastasis, but is not related to depth of tumor invasion or clinical stage (p > 0.05, respectively)." (PMID 37817249, 2023).
rheumatoid arthritis (4 papers, 2021 to 2023). A chronic, systemic autoimmune disorder characterized by inflammation in the synovial membranes and articular surfaces. "A similar lipid-linked mimetic targeting human CD22, Neu5Acα2-6Galβ1-4GlcNAc carrying a 9-N-m-phenoxybenzamide, prevented production of targeted antibodies by human memory B cells isolated from rheumatoid arthritis patients." (PMID 34065256, 2021). "Co-delivery of an antigen and a high-affinity CD22 sialomimetic in a liposome resulted in tolerance in mouse models of autoimmune hemophilia and rheumatoid arthritis." (PMID 34065256, 2021).
Sepsis (4 papers, 2020 to 2025). Sepsis is defined as life-threatening organ dysfunction caused by a dysregulated host response to infection. "It has been reported that miR-19a and CD22 could form a feedback regulation loop to regulate the responses of B cells in sepsis." (PMID 32944003, 2020). "The expression of some of those genes (FCRL1, TNFRSF13C, CD22, CD79A, POU2F2) continue to be upregulated during sepsis recovery stage too." (PMID 38898888, 2024). "Not surprisingly, most of the same pathways from sepsis and septic shock were grouped, including CD22, IL16, MHC-II, and CXCL, indicating these pathways are essential for sepsis response." (PMID 36304125, 2022).
asthma (3 papers, 2015 to 2022). "CD22 mediated BCR regulation, heme scavenging from plasma, asthma, and antigen activates B cell receptor BCR resulting in the generation of second messengers were enriched in the low-risk group." (PMID 35991543, 2022).
B-cell precursor acute lymphoblastic leukemia (3 papers, 2021 to 2025). "Patient 2, diagnosed with acute lymphoblastic B-cell leukaemia, received anti-CD19 and anti-CD22 CAR-T-cell cocktail therapy and remained in complete remission for over 4 years." (PMID 36814216, 2023).
cognitive decline (3 papers, 2022 to 2026). "Notably, targeting CD22—a negative regulator of microglial phagocytosis—in the aged brain restores microglial homeostasis and reverses cognitive decline." (PMID 41549460, 2026).
Cognitive impairment (3 papers, 2021 to 2024). Abnormal cognition is characterized by deficits in thinking, reasoning, or remembering. "Inhibition of CD22 promotes microglial phagocytosis of Ab oligomers and lessens cognitive impairment in aged mice." (PMID 38711503, 2024). "CD22 inhibition increases microglial phagocytosis of Aβ oligomers and ameliorates cognitive impairment in elderly mice." (PMID 35892682, 2022). "For instance, CD22 blocks microglia-mediated engulfment of myelin debris in the aged brain, while CD22 blockade restores microglial homeostasis and cognitive impairment in aged mice." (PMID 35082781, 2021).
esophageal cancer (3 papers, 2018 to 2025). A primary or metastatic malignant neoplasm involving the esophagus. "Our group has previously investigated several tumor-associated target in cancer, such as CD22 in breast cancer and esophageal cancer, CD276 in esophageal cancer." (PMID 41573636, 2025).
glioma (3 papers, 2021 to 2022). A benign or malignant brain and spinal cord tumor that arises from glial cells (astrocytes, oligodendrocytes, ependymal cells). "Among these pathways, many immune-related pathways were highly associated with PROS1, including CD22 mediated by regulation,immunoregulatory-Internation, chemokine receptors bind chemokines, disease of the immune system, chemokine signaling pathway, IL-18 signaling pathway in glioma." (PMID 36685506, 2022). "Furthermore, we found a significant increase of CD3, CD4, CD8, CD16, CD11, CD22 positive immune cell infiltrates in grade IV glioma tissues compared with grade II and III." (PMID 35493457, 2022).
liver cancer (3 papers, 2021 to 2024). An epithelial or non-epithelial malignant neoplasm that arises from the liver. "CD22-mediated pathways have not been enriched in CRC prevention and treatment; however, CD22 has been used as an immunotherapy target in the treatment of tumors such as triple-negative breast cancer, liver cancer, and B-cell lymphoblastic lymphoma." (PMID 37960165, 2023).
myeloid leukemia (3 papers, 2021 to 2025). A clonal proliferation of myeloid cells and their precursors in the bone marrow, peripheral blood, and spleen. "Similar to lymphoid malignancies where multiple antigens including CD19, CD20, and CD22 are being targeted, myeloid leukemias will also likely require targeting of multiple antigens either alone or in combination." (PMID 40268927, 2025).
neutropenia (3 papers, 2015 to 2026). A decrease in the number of neutrophils found in the blood. "During CD22 CAR-T therapy, grade 3 or 4 lymphocytopenia occurred in all patients, neutropenia in 87.0%, anemia in 21.7%, and thrombocytopenia in 52.2%." (PMID 39754190, 2025). "One month after CD22 CAR-T infusion, among patients with grade 3 or higher cytopenia, recovery to grade ≤ 2 lymphopenia was observed in 82.6%, neutropenia in 80%, anemia in 40%, and thrombocytopenia in 50%." (PMID 39754190, 2025).
prostate carcinoma (3 papers, 2020 to 2024). A carcinoma that arises from epithelial cells of the prostate gland. "The data presented reveals ST6GAL1 controls the expression sialoglycans on prostate cancer cells including ligands that could engage Siglec-2 (CD22) and Siglec-3 (CD33) on immune cells." (PMID 38772281, 2024). "Our findings reveal expression of ST6GAL1 alters sialoglycan patterns in prostate cancer cells, and in line with the literature, we find ST6GAL1 specifically regulates sialoglycans that engage Siglec-2 (CD22) and Siglec 3 (CD33)." (PMID 38772281, 2024).
Sjögren's syndrome (3 papers, 2006 to 2014). "This is consistent with the finding that patients with Sjögren's syndrome have an over-expression of CD22." (PMID 16859536, 2006). "This open-label, phase I/II study investigated the safety and efficacy of epratuzumab, a humanised anti-CD22 monoclonal antibody, in the treatment of patients with active primary Sjögren's syndrome (pSS)." (PMID 16859536, 2006).
systemic sclerosis (3 papers, 2011 to 2025). A chronic disorder, possibly autoimmune, marked by excessive production of collagen which results in hardening and thickening of body tissues. "Supporting this hypothesis is evidence of a role for CD22 in systemic sclerosis; anti-CD22 autoantibodies contribute to systemic sclerosis pathogenesis and there is evidence of association between a SNP in CD22 and limited cutaneous systemic sclerosis." (PMID 21247474, 2011). "For example, CD22 shows lower expression on various B-cell subsets, including transitional, naive, and particularly memory B cells in RA and on total B cells in systemic sclerosis." (PMID 39435875, 2025).
central nervous system leukemia (2 papers, 2020 to 2024). Leukemia infiltrating the central nervous system structures. "Patient 5 had evidence of CNS leukemia at the time of cell infusion that disappeared coincident with a rise in CSF-infiltrating CD19/CD22 CAR T cell numbers." (PMID 32245502, 2020). "CD19/CD22 CAR T cells also migrated efficiently to the CSF, raising the prospect that CD19/CD22 CAR T cells can prevent or treat CNS leukemia." (PMID 32245502, 2020). "The treatment of extramedullary disease with CD22 monoclonal antibody has not been studied, so the prevention of central nervous system leukemia should be strengthened." (PMID 39029009, 2024). "For all patients, the CSF showed evidence of CNS trafficking by the infused CD19/CD22 CAR T cells, and the concentrations of CSF-infiltrating CAR T cells were highest in patient 5 with CNS leukemia; however, no neurotoxicity was observed in any of the treated patients." (PMID 32245502, 2020).
cutaneous T cell lymphoma (2 papers, 2015 to 2021). "Importantly, CD22ΔN mRNA is expressed in skin lesions from 39 out of 60 patients with cutaneous T cell lymphoma (CTCL), whereas few patients (6 out of 60) expresses full-length, wild type CD22 (CD22wt)." (PMID 25957418, 2015).
glomerulonephritis (2 papers, 2012 to 2024). A renal disorder characterized by damage in the glomeruli. "CD22 deficiency alone causes an age-related expansion of autoreactive B cells without pathology, whilst double deficiency of both CD22 and Siglec-G results in glomerulonephritis." (PMID 39007135, 2024).
Lung fibrosis (2 papers, 2020 to 2022). "Lung fibrosis scores were significantly better in mutant mice (CD22-deficient, CD72-deficient and CD22 and CD72 double-deficient mice) compared to wild type mice (mice without CD22 or CD72 deficiency)." (PMID 35860745, 2022). "Thus, deficiency of CD22 or CD72 or both decreased bleomycin-induced lung fibrosis." (PMID 35860745, 2022). "However, anti-CD22 treatment preferentially depleted Bregs and attenuated lung fibrosis in mice with silica instillation-induced pulmonary fibrosis, suggesting that Bregs may promote pulmonary fibrosis." (PMID 32708044, 2020). "Loss of inhibitory molecules, either CD22 or CD72, decreased skin and lung fibrosis revealing a role for both negative co-receptors of BCR signaling in disease pathogenesis." (PMID 35860745, 2022).
lymphocytopenia (2 papers, 2020 to 2025). "Few grade 3-4 toxicities were observed with Moxe, including grade 3–4 lymphopenia and leukopenia which probably represented treatment effects due to the targeting of malignant and normal CD22+ B-cells." (PMID 32756468, 2020).
MALT lymphoma (2 papers, 2013 to 2023). An indolent, extranodal type of non-Hodgkin lymphoma composed of small B-lymphocytes (centrocyte-like cells). "MALT lymphomas express B-cell-associated antigens (CD20, CD22, and CD79a) and are negative for CD5, CD10, and CD3." (PMID 23476858, 2013).